IFNG (interferon gamma)
Diseases named in the same sentence as IFNG in open-access papers (continued):
Sharing a sentence is not in itself a finding about the gene and the disease.
pulmonary TB (179 papers, 2004 to 2026). "Three studies also reported that positive interferon-gamma release assay (IGRA) results were significantly associated with pulmonary TB (OR: 17.34; 95% CI: 6.71-44.75; I2 = 68%)." (PMID 41450404, 2025). "Several other studies have been performed on IFNγ polymorphism at the -611 position and infectious diseases, including pulmonary tuberculosis, HIV1/AIDS infection, retinochoroiditis, toxoplasmosis, and chronic hepatitis C virus infection." (PMID 31582997, 2019). "Some controversy exists concerning association of IFNG gene polymorphisms and susceptibility to pulmonary TB." (PMID 24024215, 2013). "Among 176 target genes associated with pulmonary TB, most genes were targeted by only one miRNAs in the network (IFNG was only targeted by hsa-miR-29c)." (PMID 24349033, 2013). "IRF8 and IFNγ are required for protection against pulmonary infection with M. tuberculosis, and mice bearing mutations in either gene are hyper-susceptible to pulmonary tuberculosis." (PMID 21731497, 2011). "Furthermore, the IFNG +874 T/A(rs2430561)polymorphism played an important role in protecting individuals from both pulmonary tuberculosis and extra-pulmonary tuberculosis." (PMID 28881572, 2017). "We present evidence that, as measured by IFNγ response to CFP-10, there is a high prevalence of infection in HHCs and that high HHC IFNγ producers in response to CFP-10 are at higher risk of developing TB than lower producers early after exposure to a pulmonary TB case." (PMID 20011589, 2009). "Pulmonary TB is driven by persistent inflammation, involving pro-inflammatory cytokines such as tumor necrosis factor-alpha, interleukin-6 and interferon-gamma." (PMID 40978039, 2025). "IFNα2 was detected in 74 % and 64 % of patients with sarcoidosis and pulmonary TB, respectively, while IFNγ was found in 78 % and 23 % of patients with sarcoidosis and TB, respectively." (PMID 39309852, 2024). "We conducted a concurrent adult pulmonary tuberculosis prevalence survey and a child M. tuberculosis infection survey using interferon gamma release assays in four districts (Korangi, South, West and Central)." (PMID 39196979, 2024). "Sex-specific immune responses that likely contribute to the pathogenesis of pulmonary tuberculosis include poorer specific T cell-dependent IFNγ production and lower antibody responses in men." (PMID 35454079, 2022). "In active pulmonary tuberculosis IFNγ and IL-10 are produced by Th1 T cells supporting the fact that IL-10 production is not confined to Tregs and Th2 cells." (PMID 35867720, 2022). "Jamil and colleagues established that IFNγ/IL-10 correlated with disease severity in both pulmonary TB and extrapulmonary TB." (PMID 35025927, 2022). "The patient was diagnosed with pulmonary tuberculosis based on the results of interferon gamma release assays, purified protein derivative test, and computed tomography." (PMID 33019474, 2020). "In this study, we aim to investigate the association of IFNG/IFNGR1 polymorphisms with healthy control subjects (HCS), latent tuberculosis infection (LTBI), and pulmonary TB (PTB)." (PMID 31687049, 2019). "This study compared results of interferon-gamma release assays (IGRA) between contacts of pulmonary TB patients with AFB smear positivity and those with smear negativity using QuantiFERON®-TB Gold In-Tube (QFT) assays." (PMID 31581622, 2019). "Studies have shown ability of interferon-gamma to diagnosis pulmonary tuberculosis in immune-competent individuals." (PMID 31086619, 2018). "In the current study we aimed to explore the genetic association of polymorphisms of IFNG and IFNGR1 with the risk of pulmonary tuberculosis (PTB) in the Chinese Tibetan population." (PMID 29228700, 2017). "Higher frequencies of PD-1+ T cells are observed in patients with active pulmonary tuberculosis and PD-1 blockade in vitro can enhance M. tuberculosis-specific IFNγ production." (PMID 27819295, 2016).
pulmonary TB (continued). "High levels of both TBX21 and IFNG transcripts are seen in human Crohn’s disease and TBX21 SNPs are linked with resistance to human pulmonary tuberculosis." (PMID 27530627, 2016). "Previous reports haves shown that in pulmonary TB, there is a decrease in IFNγ responses related to increased severity of disease." (PMID 19340290, 2009). "Raised M. tuberculosis - induced IFNγ in localized L-ETB as compared with pulmonary TB corresponds with previous studies employing mycobacterial antigen ESAT6 driven responses." (PMID 20041183, 2009). "Close contacts of school pulmonary TB index cases, regardless of diagnostic type, are actively screened for symptoms using interferon-gamma release assays, chest imaging, and sputum molecular diagnostic testing to detect TB infection and exclude active TB." (PMID 42247627, 2026). "In human pulmonary Tb, it has been described that there is a relationship between the production of IFNγ and the clinical manifestations of the disease; the more severe the disease, the lower levels of IFNγ are produced by peripheral blood mononuclear cells." (PMID 36671276, 2022). "However, for diagnosis of pulmonary tuberculosis, IFNγ alone has limitations relating to sensitivity." (PMID 33767693, 2021). "Diagnostic performance of interferon-gamma release assays (IGRA) tools to discriminate nontuberculous mycobacterial (NTM) from pulmonary tuberculosis (PTB)." (PMID 33680977, 2020). "Diagnostic performance of interferon-gamma release assay (IGRA) tools to discriminate species of nontuberculous mycobacterial (NTM) from pulmonary tuberculosis (PTB)." (PMID 33680977, 2020). "Previous studies indicated that single-nucleotide polymorphisms (SNPs) of interferon gamma (IFNG) and IFNG receptor 1 (IFNGR1) may be involved in the pathogenesis of pulmonary tuberculosis (PTB) in different populations." (PMID 31687049, 2019). "The aim of our study was to investigate whether IL6–174 G>C SNP and IL17A -197 G>A polymorphism and additional cytokine genes involved in immune response to MTB (IL2, IL4, IL10, IFNG and TNF) are associated with genetic susceptibility to pulmonary TB (PTB)." (PMID 26840977, 2016). "The increased effector T cell IFNγ response in the L-ETB group as compared with pulmonary TB may reflect a reduction in IFNγ with increasing mycobacterial load, inflammation and clinical severity." (PMID 20041183, 2009). "Besides, IFNG rs1861493 SNP and rs1861494 SNP were associated with susceptibility to pulmonary tuberculosis, but the contribution of each one was not clarified." (PMID 29361774, 2018). "Therefore, the aim of this study was to verify if IFNG, IL12B, TNF, IL17A, IL10, and TGFB1 gene polymorphisms influence the immune response of Brazilian patients with pulmonary tuberculosis (PTB) at different time points of antituberculosis treatment (T1, T2, and T3)." (PMID 23634300, 2013). "Exposure to pulmonary tuberculosis (PTB) culminates in heterogeneous outcomes, including variation in Mtb antigen-specific interferon-gamma (IFN-γ) T-cell responses." (PMID 39606489, 2024). "Pulmonary TB screening and close-contact investigation were conducted using acid-fast staining, sputum culture, GeneXpert testing, tuberculin skin testing (TST), interferon-gamma release assay (IGRA), and chest computed tomography (CT)." (PMID 37497034, 2023). "Between 2008 and 2013, we identified culture-positive pulmonary TB patients and evaluated their household contacts with both a TST and interferon gamma release assay (IGRA), and identified TST converters at 8–12 weeks post study enrollment." (PMID 28821234, 2017). "This list shows a 43% overlap with our list of IRF8 binding peaks, a 21% overlap with our list of genes regulated by IFNγ/CpG in a IRF8-dependent fashion, and 70% overlap with the list of genes differentially regulated during pulmonary tuberculosis in vivo." (PMID 21731497, 2011).
pulmonary TB (continued). "The BCG-induced IFNγ responses which were depressed in TB patients compared with both TST- ECS and TST+ ECS healthy controls also confirm our previous reports on pulmonary TB patients." (PMID 20041183, 2009). "In another patient (patient 5), obsolete pulmonary tuberculosis was diagnosed due to obsolete lung lesion on chest enhanced CT scan, positive interferon gamma release assay, and positive tuberculin skin test without evidence of active tuberculosis infection." (PMID 34660491, 2021). "Among sputum-negative and non-sputum-producing pulmonary TB suspects, the positivity of Mtb detection in BALF is associated with a younger age, the presence of pulmonary cavities and a positive result of interferon-gamma release assay (IGRA)." (PMID 29580276, 2018). "DosR antigens Rv2029c of M. tuberculosis induced higher frequencies of CD4+ or CD8+ T cells producing interferon gamma (IFN-γ) and/or tumor necrosis alpha (TNF-α) in patients with long-term latent tuberculosis infection (ltLTBI), compared to those with pulmonary tuberculosis (PTB)." (PMID 29204139, 2017). "We determined interferon-gamma, interleukin-10, and adiponectin levels in clinically and phenotypically well-characterised non-substance using new pulmonary tuberculosis patients (n = 13) and controls (n = 14) from Kenya." (PMID 26880909, 2016). "Moreover, we observed that Ciita expression is tightly regulated by IFNγ/CpG in an IRF8-dependent fashion in macrophages from F2 mice (2×2 interaction Anova analysis), and is also regulated in pulmonary tuberculosis." (PMID 21731497, 2011). "Furthermore, in a Japanese study, no anti-IFNγ auto-antibodies were found in 189 pulmonary TB patients." (PMID 38203686, 2023). "A similar IFNγ treatment study with pulmonary TB patients showed no significant changes in disease morphology as observed by chest radiology results, however the IFNγ treatment did attenuate general disease symptoms such as fever and increased rates of sputum smear conversion." (PMID 32849525, 2020). "In this study, serum levels of interferon gamma (IFN-γ), matrix metalloproteinases 1 and 9 (MMP-1 and MMP-9, respectively), and periostin were compared between 40 pulmonary tuberculosis (PTB) and 28 non-tuberculous pneumonia (non-PTB) patients." (PMID 31917802, 2020).
inflammatory bowel disease (176 papers, 2008 to 2025). A spectrum of small and large bowel inflammatory diseases of unknown etiology. "Polymorphisms in the IFNγ gene are associated with disease severity in major forms of human inflammatory bowel diseases (IBDs), such as Crohn’s disease and ulcerative colitis." (PMID 36499642, 2022). "Aberrant interferon gamma (IFNγ) expression is associated with the pathogenesis of numerous autoimmune- and inflammatory disorders, including inflammatory bowel diseases (IBD)." (PMID 29416538, 2018). "For instance, IFNγ may increase the risk of developing inflammatory bowel diseases by impairing Paneth cell viability and jeopardizing enteric homeostasis, despite its beneficial roles in suppressing colorectal CSCs and arresting cancer cell proliferation." (PMID 37671945, 2023). "As we presented in the introduction, aberrant IFNγ signaling is associated with ulcerative colitis, a chronic inflammatory bowel disease (IBD)." (PMID 38684864, 2024). "In Inflammatory Bowel Disease (IBD), patients with Crohn's disease have a loss of colonic or ileum IL-22-producing ILCs (including ILC3s) and an increase in IFNγ/IL-17A-producing ILCs." (PMID 30984202, 2019). "T cells producing IFNγ play a pathogenic role in the development of inflammatory bowel disease (IBD)." (PMID 30333822, 2018). "Next, we tested the function of TNFα- and IFNγ-licensed MSCs by employing dextran sulfate sodium (DSS)-induced inflammatory bowel diseases (IBD) model in C57BL/6 J mice." (PMID 36195887, 2022). "Our study is aimed at comparing the interferon-gamma release assay and tuberculin skin test to determine the prevalence of latent tuberculosis in inflammatory bowel disease patients in the Indian subset of patients." (PMID 33575041, 2021). "In an in-vitro study, a significant reduction was seen in several inflammatory biomarkers including tumor TNF-α, IL-1α, IL-6, IL-8, T-cell interferon-gamma (IFN-γ), and IL-2, in the presence of ≥10 μg/ml garlic extract in inflammatory bowel disease." (PMID 30683061, 2019). "PTPN2 has been known as a negative regulator of inflammatory signaling in the interferon gamma (IFN-γ)-treated THP-1 cells or inflammatory bowel disease." (PMID 27611995, 2016). "TNFα and IFNγ are proinflammatory cytokines involved in mediating the intestinal epithelial barrier dysfunction observed in inflammatory bowel diseases, and numerous studies have demonstrated their role in disruption of epithelial apical junction structure." (PMID 27119373, 2016). "Because of the innate and adaptive features of these cells, and the ability to produce high levels of IL-4 and IFNγ, a role for iNKT cells has been suggested in inflammatory bowel disease and in CD." (PMID 26529008, 2015). "In a murine model of inflammatory bowel disease, the infusion of interferon gamma-stimulated monocyte-derived cells (IFNγ-MdC) procured from mouse spleen, blood, and bone marrow reduced inflammation from chronic colitis." (PMID 22826708, 2012). "The cytokines TNF (TNFSF2) and IFNγ are important mediators of inflammatory bowel diseases and contribute to enhanced intestinal epithelial permeability by stimulating apoptosis and/or disrupting tight junctions." (PMID 21853060, 2011). "Mice with targeted deletion of Gαi2 develop an inflammatory bowel disease closely resembling ulcerative colitis, and the IFNγ and IL1β levels were increased in the inflamed colons." (PMID 19238203, 2009). "These animals were also shown to develop a spontaneous inflammatory bowel disease (IBD) associated with increased abundance of CD4+ T cells expressing the pro-inflammatory cytokines IL17, interferon gamma (IFNγ), and tumor necrosis factor alpha (TNF⍺) in the colonic lamina propria." (PMID 32598378, 2020). "Crohn’s disease (CD) is a chronic inflammatory bowel disease (IBD) and is considered a Th1-mediated disease, supported by the over-expression of interferon-gamma (IFN-γ) in the intestinal lamina propria." (PMID 40230837, 2025).
inflammatory bowel disease (continued). "Interestingly, IFNγ-dependent gene modules were also induced in EGCs from patients with inflammatory bowel disease and chemokine interferon-γ-inducible protein (CXCL10) has been shown to be an “early immediate response” by EGC in response to intestinal injury-induced interferon λ signaling." (PMID 38147796, 2024). "The dysregulated IFNγ signaling is often found in the pathophysiology of inflammatory bowel diseases (IBD)." (PMID 38684864, 2024). "Increased expression of IFNγ highly correlates with the severity of chronic inflammatory disorders, including systemic lupus erythematosus and inflammatory bowel disease (IBD)." (PMID 36499642, 2022). "On the other hand, NKp44-ILC3 have been described to accumulate and to aggravate inflammation due to their secretion of IFNγ and IL-17A, respectively, especially during inflammatory bowel disease (IBD)." (PMID 35003122, 2021). "Genes in the kidney network are also enriched for interferon-gamma production and inflammatory bowel disease (IBD)." (PMID 31562339, 2019). "Increased production of pro-inflammatory cytokines, including interferon gamma (IFN-γ), TNF-α, IL-1 and IL-13 further exacerbate damage to the intestinal mucosa, as occurs in inflammatory bowel disease (IBD)." (PMID 39273791, 2024). "In case of inflammatory bowel disease, BBR is known to induce protective immune responses by modulating IFNγ and IL17 CD4+ T cells by activation of AMP kinase." (PMID 36881595, 2023). "In the context of inflammatory bowel disease, CD8+γδ T cells have been shown to have cytotoxic potential, able to produce IFNγ and TNF, and correlate negatively with disease activity." (PMID 35922467, 2022). "Seven genes IL10, IL4, IL6, IFNG, IL1B, TNF and IL17A, were engaged in Inflammatory bowel disease." (PMID 36989283, 2023). "Rag-/-/SCID: Recombination activating genes knockout model/severe combined immunodeficiency; TNF: Tumor necrosis factor; UC: Ulcerative colitis; TLR: Toll-like receptors; Treg cells: Regulatory T cells; CD40LTG: CD40 ligand transgene; IFNγ: Interferon-gamma; IBD: Inflammatory bowel disease." (PMID 36039239, 2022). "Pathogenicity may reflect the modest switch to expression of the pathogenic cytokines IFNγ, IL-17A, and F, although in other models of inflammatory bowel disease (IBD), the percentage of IFNγ producers can be much higher." (PMID 26834739, 2015). "Inflammatory bowel disease (IBD) is characterized by an imbalanced immune response, leading to a pro-inflammatory phenotype with elevated tissue concentrations of various cytokines including tumor necrosis factor (TNF), interleukin-6 (IL-6), and interferon-γ (IFNγ)." (PMID 31572379, 2019). "Interferon-gamma (IFN-γ) and tumor necrosis factor-alpha (TNF-α), derived from T cells, are key mediators of intestinal inflammatory diseases, including inflammatory bowel disease (IBD)." (PMID 40370438, 2025). "We estimate the prevalence of positive interferon gamma release assay (IGRA) tests (including TB) and TBI (excluding TB) in Denmark based on TBI screening data from patients with inflammatory bowel disease (IBD) or inflammatory rheumatic disease (IRD)." (PMID 38516789, 2024). "Moreover, IECs isolated from patients with inflammatory bowel disease (IBD) expressed MHC II, CD80 and CD86 and were found capable of inducing CD4 T cell proliferation and IFNγ secretion." (PMID 31316504, 2019). "The seRNAs IFNG-r-49 regulates the expression of IL-26 and IL-22 in inflammatory bowel disease (IBD), but does not regulate the expression of IFNG." (PMID 36726725, 2023). "Unlike inflammatory bowel diseases, there is lack of clear TH1 or TH2 skewing in ASD with the observation that IL-4, IL-2, and interferon gamma (IFN-γ) are elevated in the duodenal mucosa while IL-4 is elevated in the colon." (PMID 29868601, 2018).
inflammatory bowel disease (continued). "Therefore, since 2009, Danish guidelines have recommended systematic screening by interferon gamma release assays (IGRA) for TBI regardless of exposure to M. tuberculosis before initiation of biological agents to treat inflammatory bowel disease (IBD) and rheumatic disease (IRD)." (PMID 38516789, 2024).